MUC1 (mucin 1, cell surface associated)
Diseases named in the same sentence as MUC1 in open-access papers (continued):
Sharing a sentence is not in itself a finding about the gene and the disease.
tumor (continued). "Calycosin regulated MUC1, Atg5 protein expression snail protein, G1 phase arrest, and TGF‐β in MIA‐PaCa2 cell line at 50–100 μM, leading to cause apoptosis and autophagy, while at 30 mg/kg prevent tumor growth in C57/BL6 mice." (PMID 38230908, 2024). "The MUC1.Tg female mice were injected intraperitoneally with 2F8cis tumor cells." (PMID 38339228, 2024). "In addition, immunohistochemical analysis showed that MUC1 protein was expressed in the cytoplasm of tumor cells." (PMID 38592620, 2024). "In this study, we judiciously constructed a recombinant MUC1-dependent adenovirus (rAdF35-MUC1) that can selectively replicate and overexpress copepod super green fluorescent proteins (copGFP) in MUC1-positive tumor cells to investigate its role in the detection of CTCs." (PMID 39886667, 2024). "In addition, the high expression of MUC1 drove monocytes to differentiate into TAMs, which also promoted the migration and invasion of tumour cells." (PMID 38778448, 2024). "This arrangement maintains MUC1 specificity of tumor targeting." (PMID 38745414, 2024). "Therefore, the study of MUC1 and the preparation of anti-tumor drugs against MUC1 are of great importance for the comprehensive treatment of cancer." (PMID 38164273, 2024). "MUC1 is one of the most attractive tumor antigens for the immunotherapy of various tumors." (PMID 37489369, 2023). "Various glycosaminoglycans (hyaluronic acid, heparin) and proteoglycans (CD44, CSPG4, MUC-1) have been suggested as potential cancer targets due to their important roles in tumor pathogenesis and their upregulation in malignant tissues but are also expressed in healthy tissues." (PMID 37118819, 2023). "In addition, sialic acid glycans on MUC1 can bind to lectins to promote the adhesion of cancer cells to vascular endothelial cells or promote the production of the tumor microenvironment, which is conducive to cancer progression and metastasis." (PMID 37894512, 2023). "Furthermore, our study showed the MUC1-CD3 BsAb can potently suppress MUC1-positive tumor growth in a xenograft mouse model." (PMID 37489369, 2023). "The administration of DCs loaded with MUC1-derived peptide, alone or in combination with other tumor-specific antigens, has been tested in several clinical trials for patients with refractory NSCLC, pancreatic cancer, biliary cancer, and castration-resistant prostate cancer (CRPC)." (PMID 36900399, 2023). "First, a panel of tumor cell lines was analyzed by flow cytometry for MUC1 surface expression." (PMID 37489369, 2023). "In addition, the expression level of MUC1 in tumor tissue was higher than that in normal liver tissue (P = 0.0462) according to TCGA and GTEx data." (PMID 36738352, 2023). "As for MUC1, the median tumor H-score value was 210 (IQR: 157.5–260)." (PMID 37760554, 2023). "In addition, the tumor size distribution showed that in MUC1.Tg mice vaccinated with MUC1 + BMDCs, the frequency of smaller tumors (1 mm2) was highest, while that of larger tumors (ranging from 3 mm2 to 54 mm2) was lowest compared to all other groups." (PMID 36980805, 2023). "For instance, theglycoprotein MUC1 is overexpressed in many tumor tissues and tendsto carry simple oligosaccharides that allow for the presentation ofdifferent tumor-associated antigens, such as the Tn or sTn antigens(GalNAc-α-1-O-Thr/Ser and Neu5Acα2-6GalNAcα1-O-Ser/Thr,respectively)." (PMID 36815693, 2023). "The Tn glycan epitope presented on tumor-associated glycoproteins has also been demonstrated to be a target for macrophage galactose-type lectin receptor (MGL, CD301) which can discriminate between healthy and tumor-associated glycans of the mucin MUC1." (PMID 36726757, 2023). "Indeed, MUC1-targeting CAR Ms showed potent anti-tumor function by phagocytosis and secretion of pro-inflammatory cytokines such as IL-1β, IL-8, and TNFα in the presence of MUC1 expressing tumor cells from solid lung tumors or malignant pleural effusions." (PMID 38017494, 2023).
tumor (continued). "In addition, studies in human MUC1-transgenic (MUC1.Tg) mice have shown that vaccination with MUC1 peptides and MUC1 DNA can effectively break the tolerance to injected MUC1-expressing tumor cells." (PMID 36980805, 2023). "For example, binding of galectin-3 to the oncofoetal Thomsen-Friedenreich Galβ1,3GalNAcα-Thr/Ser (TF antigen) on the transmembrane mucin protein MUC1 enhances circulating tumour cell homotypic aggregation and survival and increases tumour cell heterotypic adhesion to vascular endothelium." (PMID 37055381, 2023). "The enhanced MUC1-CAR T cells possessed durable tumor-killing and proliferative capacity." (PMID 36707873, 2023). "This structure produces representative tumor antigens and makes MUC1 a good immunotherapy target." (PMID 37457288, 2023). "The inhibition of MUC1/T antigen—galectin-3 interactions may be a potential strategy to reduce tumor progression and metastasis." (PMID 37345016, 2023). "ICAM-1 was found to bind to MUC1 at the tumor leading edge, thus promoting cell invasion." (PMID 36868311, 2023). "The N-terminal part of MUC1 acts as a cell barrier, participates in cell–cell and cell–extracellular matrix interactions, and can also be involved in signaling pathways connected with transformations related to tumor progression." (PMID 37685842, 2023). "Moreover, our study also showed this BsAb had potent efficacy in inducing T cell-mediated MUC1-positive tumor cell lysis in vitro and inhibiting MUC1-positive tumor growth in the xenograft mouse model." (PMID 37489369, 2023). "However, it must be emphasized that cancer vaccines targeting MUC1 have great anti-tumor potential when further refined and evaluated in clinical trials." (PMID 37894512, 2023). "Moreover, increasing the effector-to-target cell ratio from 2:1 to 8:1 in human T cells and tumor cells co-culture assay can further improve the T cell-mediated cytotoxicity toward MUC1-positive tumor cells." (PMID 37489369, 2023). "Overaccumulation of Tn and STn on MUC1 is particularly important for tumor cell immune escape." (PMID 37894512, 2023). "However, in squamous metaplasia, MUC1 was highly expressed, not only in the apical part of tumor cells but also on the whole cell surface and in the cytoplasm." (PMID 36980805, 2023). "Mucin 1 (MUC1) can mediate tumor invasion, and its expression depends on STAT3." (PMID 38067351, 2023). "While tumor diameter, nodal status and MUC-1 expression were similar in the two groups, the group exhibiting five immune markers contained higher HLA-DR contents (p < 0.0001) and CXCL13 expression levels (p = 0.001) than those with none of the selected markers." (PMID 36765559, 2023). "Another feature of AR20.5 is to form immune complexes with circulating MUC1 and/or MUC1-expressing tumor cells in vivo, implying that it may stimulate a dendric cell-mediated T cell response." (PMID 37509200, 2023). "Silencing MUC1 could reduce the expression of PI3K/p-Akt in tumor cells (A549/PTX) and inhibit the ability of stem cells to form spheroids." (PMID 36778203, 2023). "The MUC1 positive patients had a significantly higher proportion of diffuse- or mixed-type histology (p = 0.001), tumors invading proper muscle or deeper layer (p = 0.002), lymph node metastasis (p = 0.017), and advanced final tumor stages (p = 0.002)." (PMID 36831343, 2023). "Different from MUC1, knockdown of these genes could promote the proliferation and migration ability of tumor cells." (PMID 36899330, 2023). "Unlike MUC2, cell surface-linked Mucin 1 (encoded by Muc1) is often associated with tumor-induced changes in host immunity." (PMID 37966243, 2023). "Tumor size, PgR status, and MUC1 staining were independent factors relating to DFS." (PMID 37002293, 2023). "Thus, our findings demonstrated that the MUC1/CD3 BsAb can potentially be developed as a new therapeutic drug in clinical applications for the treatment of MUC1-positive tumor patients." (PMID 37489369, 2023).
tumor (continued). "The MGL binding is highly selective for tumor MUC1—MGL interacts with cancer-associated MUC1 but does not recognize MUC1 from normal cells." (PMID 38069400, 2023). "In addition, MUC1 acts as a modulator of chronic inflammation, although its role in regulating the tumor immune microenvironment (TME), especially in ccRCC, is poorly understood." (PMID 36902242, 2023). "As early as May 1996, the American Society of Clinical Oncology (ASCO) evaluated MUC1 and designated it as a tumor marker for BC." (PMID 37894512, 2023). "MUC1 is one of the best characterized tumor antigens, occurring in a broad spectrum of carcinomas." (PMID 38069400, 2023). "Additionally, peptide-vaccine-based immunotherapy targets tumor-associated antigens that are overexpressed on the surface of tumor cells, such as CEA, melanoma-associated antigen, and MUC1." (PMID 37686520, 2023). "Moreover, the MGL mutant was unable to recognize Tn epitopes on tumor cell lines or its previously established Tn-containing ligands such as MUC1 or mucin 2 (MUC2)." (PMID 38069400, 2023). "Notably, when we focused the analysis on receptor-positive patients, the frequency of total CD7+CD56+ NK cells exhibiting the tumor markers MUC1 and HER2 appeared to be increased." (PMID 37593736, 2023). "MUC1 is a membrane bound protein that can regulate tumor progression but its role in tumor metastasis and the metastatic microenvironment remains unclear." (PMID 36738352, 2023). "Furthermore, cell cytotoxic assay was also performed by flow cytometry and the MUC1/CD3 BsAb can induce T cell-mediated killing of MUC1-positive tumor cells in a similar pattern." (PMID 37489369, 2023). "VLPs induce the production of specific antibodies and CTL responses in mice, which could bind to and kill MUC1-expressing tumor cells through complement-mediated cytotoxicity." (PMID 37243023, 2023). "Consequently, it can access tumor-specific truncated carbohydrate antigens, such as TF and Tn, within MUC1’s VNTR region, as well as antibodies, and can reduce glycan site occupancy." (PMID 35883508, 2022). "There are some facts that MUC1 suppresses the immune response and promotes tumor growth." (PMID 35248049, 2022). "Their research was the first to demonstrate that CAR-grafted T-cells could be used to target the almost-omnipresent MUC1 tumor antigen." (PMID 35883508, 2022). "Therefore, MUC1 would be a highly attractive antigen for the development of effective anticancer vaccines and a potential molecular target for reprogramming the tumour microenvironment." (PMID 36059804, 2022). "Mucin 1 (MUC1) is an attractive target in tumor immunotherapy." (PMID 36142800, 2022). "Interfering HILPDA and MUC1 expression would inhibit tumor cell proliferation and migration, and MUC1 might improve the ferroptosis resistance of OS cells." (PMID 36439512, 2022). "However, the aberrantly O-glycosylation provides MUC1 with oncogenic biological properties to promote tumor progression, anoikis escape, and metastasis." (PMID 35970845, 2022). "In patients with disease progression, two patients showed loss of tumor MUC1 expression, and one of the patients had MUC-1-specific T cells, suggesting that tumors might evade DC vaccine-induced anti-tumor immunity by down-regulating TAAs." (PMID 35053338, 2022). "Moreover, we have demonstrated that incorporating CD28 signaling in CAR MUC1 upregulated the immunosuppressive cytokines, IL-4 and IL-10, upon encountering the targeted tumor cells." (PMID 36457849, 2022). "Interestingly, tMUC1, MUC1 in an abnormally glycosylated tumor form, shows overexpression in over 95% of TNBC cases, but it is rarely expressed in healthy mammary tissues." (PMID 35883508, 2022). "Anti-MUC1 CAR-T cells showed increased proliferation and IL2 secretion upon the stimulation and could effectively kill MUC1-positive tumor cell lines." (PMID 36123710, 2022).
tumor (continued). "Among the DEGs identified in malignant cells in SBA, MUC1 is widely expressed in different patients, and the IHC staining confirmed the specificity of MUC1 in tumor tissues of SBA, which indicates that MUC1 can be regarded as a universal marker of SBA according to our scRNA-seq data." (PMID 36104333, 2022). "Furthermore, we used GEPIA to compare the expression of MUC1 in normal and tumor tissues and found that the mRNA expression of MUC1 significantly increased in tumor tissues (p value < 0.01)." (PMID 35879749, 2022). "Consequently, blocking tandem repeats of MUC1 is theoretically an effective way for suppressing tumor propagation." (PMID 34694686, 2022). "Following processing of this complex with APCs, cytotoxic T lymphocytes will become activated in response to interconnection with APCs through MHC type I and will transmigrate to tumor site where they can recognize Muc1‐expressing tumor cells and induce apoptosis and induce killing of tumor cells." (PMID 34694686, 2022). "Our study found seven downstream factors that may be associated with chemoresistance, LTF, SOD2, STAT1, CDKN2A, CD81, RAC1, and NDRG1 and five factors that may be associated with tumor development, CCN1, DCTN3, MUC1, H1-5, and SLC1A5." (PMID 35421932, 2022). "Mucin 1 (MUC1) is a heterodimeric protein formed by two subunits that is highly overexpressed (until tenfold) on the surface of cancer cells in most malignant tumors including ovarian, lung, pancreatic, prostate, and breast cancers." (PMID 35304550, 2022). "Therefore, it can be concluded that combination of CTLA-4 blockade with MUC1 mRNA nanovaccine enhances anti-tumor cytotoxic T-lymphocyte activity by reducing immunosuppressive TME and inhibiting tumor-promoting STAT3 signaling pathway." (PMID 34875483, 2022). "Specific recognition mucin 1 (MUC1) is overexpressed on the surface of most tumor cells." (PMID 35953863, 2022). "Also, a significant decline in expression of Ki‐67, MMP9, and VEGFR2 biomarkers, as well as vasculogenesis, was evident in immunohistochemically stained tumor sections of anti‐MUC1 nanobody‐treated mice." (PMID 34694686, 2022). "And so far, many scholars have studied the anti-tumor efficacy of DC vaccine targeting MUC1." (PMID 35891256, 2022). "Taken together, these results indicate that this novel PD-L1-containing MUC1-Vax-DC vaccine can inhibit the growth of MUC1+ and PD-L1+ tumor cells, and may be an effective therapeutic vaccine against MUC1+ and PD-L1+ tumors." (PMID 35891256, 2022). "In this case, after considering challenges such as the suitable design of antibodies, therapeutic agents based on the MUC1 antibody could be effective and safe anti-tumor therapeutic approaches." (PMID 35883508, 2022). "Mice bearing mucin 1 (MUC1)-positive tumor cells were protected by MUC1-transfected DCs." (PMID 35806328, 2022). "The conserved MUC-1 peptide and dendritic cells (DCs) induced immune response against tumor cells." (PMID 35000604, 2022). "Moreover, mucin 1 protein coded by MUC1 is an important barrier to the penetration of drugs and takes part in the inhibition of apoptosis in tumor cells." (PMID 35664298, 2022). "MUC1 is overexpressed and has been identified as a potential target for diagnosis, prognosis, and therapy in most human cancers and plays an important role in tumor progression." (PMID 36012492, 2022). "Furthermore, cancer cells that express MUC1 display increased sialyl-Tn antigen, and alterations in MUC1 affect immune detection and increase macrophage activation through binding to sialylated MUC1, promoting tumor growth." (PMID 35522218, 2022). "By expression of large tumour-associated glycoproteins such as MUC1, a bulky glycocalyx on non-transformed mammary epithelial cells promoted focal adhesion assembly and facilitated integrin-dependent ERK and AKT signalling to support cell growth and survival." (PMID 35260891, 2022). "MUC1 participates in carcinogenesis and can promote tumor occurrence and development." (PMID 35883508, 2022).
tumor (continued). "MUC1 could also be involved in the exhaustion of T cell effector function in the tumor microenvironment." (PMID 35589776, 2022). "•Combination treatment with anti-CTLA-4 mAb and MUC1 mRNA nanovaccine could appear more effective than either nanovaccine or anti-CTLA-4 mAb alone at increasing level of apoptosis in tumor cells." (PMID 34875483, 2022). "Several TAAs are overexpressed in HCC to meet the increased nutrient demand of tumor cells caused by their enhanced proliferation, such as receptors for asialoglycoproteins, transferrin, and folic acid, or correlate with the exacerbation of tumor features, such as MUC1, CEA, and TEM1." (PMID 36077433, 2022). "BC patients with high expression of MUC1 showed advanced N stage, M stage, and tumor status." (PMID 35879749, 2022). "Administration of anti‐MUC1 nanobody could significantly enhance suppression of tumor growth and delay logarithmic phase of tumor growth." (PMID 34694686, 2022). "In conclusion, the anti‐MUC1 tandem repeat nanobody of the present study could effectively overcome tumor growth, invasion, and metastasis." (PMID 34694686, 2022). "Using PMIP- a peptide- that targets MUC1 significantly decreases tumor growth in the mice model." (PMID 35248049, 2022). "Staining mouse tumor sections with anti‐MUC1 nanobody and irrelevant recombinant Llama anti‐GFP nanobody demonstrated a high reactivity for anti‐MUC1 nanobody toward mouse MUC1 but a very low or negligible one for irrelevant recombinant Llama anti‐GFP nanobody." (PMID 34694686, 2022). "MUC1 expression was detectable in each of the seven tumor clusters (right)." (PMID 35612556, 2022). "In addition to its role in regulating tumor cell survival, invasion and migration, recent findings indicate that MUC1 induces transcriptional modifications that result in metabolic reprogramming." (PMID 36430448, 2022). "Heavy glycosylation of tumor-derived MUC1 causes its long-term retention in early endosomes without degradation, posing a barrier to DC presentation." (PMID 36497322, 2022). "The GC base pair on the crosslinking network provides a reliable loading site for the chemotherapy drug Dox, and in order to give the SDH tumor targeting, it is further modified with the MUC1 aptamer to identify MUC1 glycoproteins that are overexpressed on many cancer cell membranes." (PMID 35162990, 2022). "In 2016, an anti-tumor vaccine based on MUC1 (MUC1-maltose-binding protein (MBP)/BCG) entered preclinical trials and showed no significant toxicity in mice, rats or crab-eating monkeys.MUC1-MBP/BCG acts as an anti-tumor agent by inducing Th1 cell activation and MUC1-specific IgG antibody secretion." (PMID 35879749, 2022). "Confirming our hypothesis, neutralizing TGF-β treatment in high-MUC1 HPAFII tumors significantly reduced tumor progression and reduced tumor burden, whereas the same treatment almost hastened tumor growth in low MUC1 MiaPaca2 tumors." (PMID 35237602, 2022). "A nonglycosylated vaccine for MUC1 can only recognize the nonglycosylated peptide but not tumor-associated MUC1 that is aberrantly glycosylated." (PMID 36497322, 2022). "Likewise, TnMUC1, MUC1 in an abnormally glycosylated tumor form, also shows a high expression level in TNBC." (PMID 35883508, 2022). "A novel multifunctional oligonucleotide nanocarrier complex, which consists of a tumor-targeting aptamer sequence specific to MUC1, a polycytosine region for fluorescent silver nanocluster (AgNC) synthesis, and a complementary sequence for miR-34a loading, has been designed." (PMID 35154471, 2022).